SGCE (sarcoglycan epsilon)
Description:
Component of the sarcoglycan complex, a subcomplex of the dystrophin-glycoprotein complex which forms a link between the F-actin cytoskeleton and the extracellular matrix.
Synonyms: Epsilon-SG; ESG; DYT11
Tractability: Antibody: its Gene Ontology location is reachable by antibodies, with high confidence; UniProt places it where antibodies can reach, with medium confidence; UniProt predicts a signal peptide or a membrane-spanning region; the Human Protein Atlas places it where antibodies can reach. PROTAC: UniProt records ubiquitination sites on it; ubiquitination databases record sites on it.
Gene: Protein-coding gene on chromosome 7 (94,524,204 to 94,656,572, reverse strand). Ensembl gene ENSG00000127990.
Subcellular location: Cell membrane, sarcolemma; Cytoplasm, cytoskeleton; Cell projection, dendrite; Golgi apparatus
Subcellular location (Human Protein Atlas): Plasma membrane; Vesicles; Golgi apparatus; Nucleoplasm
Pathways (Reactome):
Extracellular matrix organization: Formation of the dystrophin-glycoprotein complex (DGC)
Gene Ontology:
Biological process: cell-matrix adhesion; muscle organ development; synaptic signaling
Cellular component: dystrophin-associated glycoprotein complex; dendrite membrane; endoplasmic reticulum membrane; Golgi apparatus; Golgi membrane; plasma membrane; sarcoglycan complex; cytoskeleton; dendrite; membrane; sarcolemma; synapse
Genetic constraint (gnomAD): Loss-of-function variants: 15 observed, 36.76 expected, observed/expected ratio (o/e) 0.41, 90% interval 0.27 to 0.63. The upper end of that interval is the gene's LOEUF score, 0.63, which puts it in group 2 of 6, group 1 being the genes least tolerant of losing a copy. Missense variants: 353 observed, 431.78 expected, observed/expected ratio (o/e) 0.82, 90% interval 0.75 to 0.89. Synonymous variants: 145 observed, 157.11 expected, observed/expected ratio (o/e) 0.92, 90% interval 0.81 to 1.06.
Homologues: Orthologues: chimpanzee SGCE (99% identical), pig SGCE (98% identical), macaque SGCE (97% identical), rabbit SGCE (96% identical), dog SGCE (96% identical), mouse Sgce (95% identical), rat Sgce (94% identical), tropical clawed frog sgce (84% identical), guinea pig SGCE (82% identical), zebrafish sgce (78% identical), Drosophila melanogaster Scgalpha (22% identical), Caenorhabditis elegans sgca-1 (20% identical). Paralogues in human: SGCA (39% identical).
Diseases named in the same sentence as SGCE in open-access papers:
SGCE is named in the same sentence as 54 diseases in open-access papers, as found by Europe PMC text mining. Sharing a sentence is not in itself a finding about the gene and the disease. The quoted sentences say what the papers report.
Dystonia (39 papers, 2009 to 2025). An abnormally increased muscular tone that causes fixed abnormal postures. "Myoclonus-dystonia syndrome (MDS) presents with both rapid myoclonus and dystonia, which is caused by mutations in the sarcoglycan (SGCE) gene." (PMID 38628998, 2024). "Myoclonus dystonia (DYT11) is a movement disorder caused by loss-of-function mutations in SGCE and characterized by involuntary jerking and dystonia that frequently improve after drinking alcohol." (PMID 31868164, 2019). "SGCE (Sarcoglycan, Epsilon) is a Protein Coding gene which is associated with myoclonic, dystonia-11, or dystonia." (PMID 26964035, 2016). "Myoclonus–dystonia is inherited in an autosomal dominant fashion with mutations in the maternally imprinted SGCE gene (DYT11) observed in a proportion of cases." (PMID 27242657, 2016). "Although genetically heterogeneous, most hereditary forms of myoclonus-dystonia are due to mutations in the ε-sarcoglycan gene (SGCE)." (PMID 24716024, 2014). "Pathogenic variants in SGCE (Chr 7q21.3), a maternally imprinted gene, have been causally linked to Myoclonus-Dystonia (M-D) which is most commonly characterized by childhood onset of myoclonus and dystonia." (PMID 33200041, 2020). "For example, patients with DYT1 dystonia often misdiagnosed as PD due to a prominent dystonic tremor or patients with myoclonus-dystonia due to mutations in the SGCE gene that exhibit parkinsonian features may even have a good response to high-dose levodopa treatment." (PMID 34360863, 2021). "Other genes found to be associated with isolated or combined dystonia include ANO3 (DYT24), TUBB4A (DYT4), GCH1 (DYT5a), TH (DYT5b), TAF1 (DYT3), PRKRA (DYT16), ATP1A3 (DYT12), SGCE (DYT11), KCTD17, and CACNA1A." (PMID 33051750, 2021). "Myoclonus-dystonia (DYT11) is an inherited form of dystonia caused by loss-of-function mutations in the SGCE gene, which encodes the protein epsilon sarcoglycan (ε-SG)." (PMID 31868164, 2019). "The majority (n=43) were carriers of heterozygous variants in genes linked to dominantly inherited dystonia genes (ATP1A3, GCH1, SGCE, KMT2B, THAP1, TOR1A, and VPS16), while only one carrier of a homozygous PLA2G6 variant and one of compound-heterozygous PTS variants were identified." (PMID 40672488, 2025). "Dominant SGCE mutations are a reported cause of myoclonus–dystonia, a phenotype not compatible with that seen in our patients." (PMID 37070754, 2023). "The most frequently implicated genes included the well‐established isolated and combined dystonia genes VPS16 (n = 17 index patients), THAP1 (n = 14), GCH1 (n = 13), SGCE (n = 12), GNAL (n = 8), and KMT2B (n = 8)." (PMID 40533913, 2025). "Multiple CNVs affecting SPG7 (n = 4), CACNA1A (n = 3), SGCE (n = 3), NKX2-1 (n = 2) and SPAST (n = 2) were detected in individuals with episodic ataxia, dystonia, or spastic paraplegia, respectively." (PMID 36781956, 2023). "SGCE, the epsilon member of sarcoglycan family, was demonstrated to be involved in myoclonus-dystonia syndrome (MDS) which is characterized by rapid myoclonic jerks and dystonia." (PMID 21767414, 2011).
myoclonus dystonia (31 papers, 2011 to 2026). "Her genetic test revealed a pathogenic variant of the SGCE gene, confirming the diagnosis of SGCE myoclonus dystonia." (PMID 40717718, 2025). "Only one study investigated EMG–EEG and EMG–EMG coherence in 20 patients (5 of whom were asymptomatic) with myoclonus dystonia caused by SGCE gene mutation." (PMID 39691090, 2025). "Myoclonus Dystonia, caused by SGCE mutations encoding the ε-sarcoglycan protein, represents one of now >50 monogenic forms." (PMID 39329704, 2024). "In summary, this study demonstrates an increase in cortical glutamatergic neuronal activity in the context of SGCE mutations, known to result in the hyperkinetic movement disorder, myoclonus dystonia." (PMID 36204995, 2023). "Heterozygous truncating mutations in the SGCE gene lead to myoclonus-dystonia syndrome (OMIM: 159900), characterized by myoclonic jerks affecting mainly proximal muscles." (PMID 37916192, 2023). "Myoclonus dystonia is a movement disorder caused by mutations in the SGCE gene." (PMID 40711998, 2026). "SGCE myoclonus dystonia is a rare genetic movement disorder caused by mutations in the SGCE gene." (PMID 40717718, 2025). "SGCE is a component of the sarcoglycan complex that forms a link between the F-actin cytoskeleton and the extracellular matrix, and defects in its components have been shown to be associated with myoclonus-dystonia syndrome and cardiomyopathy." (PMID 39553847, 2024). "Notably, mutations in the human SGCE gene cause the movement disorder myoclonus dystonia and autosomal recessive limb-girdle muscular dystrophies." (PMID 32753528, 2020). "Remarkably, SGCE, CACNA1B, and GRIN2A are well-known for causing Myoclonus-Dystonia (M-D), a hyperkinetic movement disorder that resembles tics, which is found in a subgroup of PANS." (PMID 35773312, 2022). "A 2 Mb deletion impacting 15 genes–including PPP1R9A and the sarcoglycan epsilon (SGCE) gene - was found in a 12 year old girl (case 7D) referred for myoclonus dystonia, short stature, failure to thrive, severe anxiety and obsessive-compulsive behavior." (PMID 27363808, 2016). "One of the most useful parts of this paper was the clear summary of previous studies on DBS in myoclonus dystonia, suggesting that DBS is effective particularly in patients known to have a mutation in the SGCE gene." (PMID 27137203, 2016). "Patients with myoclonus dystonia (caused by mutations of the SGCE gene, DYT11) have been shown to have impaired saccadic adaptation." (PMID 24872202, 2014). "Mutations in the maternally imprinted SGCE gene have been found to be the cause of developing myoclonus dystonia syndrome and psychiatric disorders, but no ART-associated defects in humans have been reported to date." (PMID 36647174, 2023). "Thirteen studies explored genetically homogeneous cohorts, involving DYT1 (TorsinA mutation) (n = 3) and DYT6 (THAP1 mutation) (n = 1, or both n = 2), DYT3 (n = 2), X‐linked dystonia parkinsonism (DYT12, ATP1A3 mutation, n = 2), myoclonus dystonia (DYT11, SGCE mutation, n = 2) and DYT27 (n = 1)." (PMID 35785410, 2022). "This study reports outcome in two patients with myoclonus dystonia, one with a proven SGCE mutation, and one with probable myoclonus dystonia by clinical criteria but negative for known pathogenic mutations." (PMID 27137203, 2016). "Analysis of the TOR1A, THAP1, and SGCE genes excluded dystonia type 1, 6 (DYT1, DYT6) and myoclonus dystonia (DYT11)." (PMID 38916623, 2024). "However, it is important to note that the aetiology of gene-negative myoclonus dystonia remains unclear, and is likely to differ from disease due to SGCE mutations, which could have important implications for treatment." (PMID 27137203, 2016). "Thus, if, for instance, the patient with childhood-onset, paternally inherited myoclonus dystonia from our previous example (see “Single-gene Sanger sequencing”), does not harbor small sequence changes in the SGCE (or KCTD17) gene, analysis of CNVs in SGCE would be warranted." (PMID 33876307, 2021).
Myoclonus (13 papers, 2014 to 2025). Very brief, involuntary random muscular contractions occurring at rest, in response to sensory stimuli, or accompanying voluntary movements. "In most cases, it is related to epsilon‐sarcoglycan (SGCE) gene mutations with autosomal dominant inheritance and reduced penetrance, configuring the SGCE‐related‐myoclonus‐dystonia (or DYT‐SGCE)." (PMID 34217152, 2022). "Interestingly, patients with myoclonus caused by SGCE mutations frequently have comorbid psychiatric symptoms, including depression, anxiety, bipolar disorder, and OCD85, symptoms that overlap with PANS." (PMID 35773312, 2022).
breast carcinoma (6 papers, 2020 to 2024). "Kaplan-Meier curves show that SDC1, NACAD, ZMAT3, CCND2, XG and SGCE are associated with prognosis in breast cancer patients." (PMID 39664194, 2024). "Conversely, EMI domain containing 1 (EMID1) and sarcoglycan epsilon (SGCE) displayed hazard ratios less than 1, suggesting a favorable prognosis for breast cancer patients with higher expression levels." (PMID 38300336, 2024). "Unfortunately, we failed to obtain an antibody for IHC to analyze the expression of SGCE in clinical breast cancer samples." (PMID 37838174, 2023). "We also found SGCE to be more highly expressed in TNBC than in other subtypes of breast cancer." (PMID 32714745, 2020). "Several new membrane proteins and prognostic markers have been reported to regulate stemness in specific subtypes of breast cancer, such as protein C receptor (PROCR), tetraspanin 8 (TSPAN8), tumor endothelial marker 8 (TEM8), epsilon sarcoglycan (SGCE), and Ki-67." (PMID 36230903, 2022). "To investigate whether SGCE is a functional gene in BCSCs, we examined cancer stemness properties using flow cytometry analysis of BCSC markers as well as suspension tumorsphere and clonal formation assays in breast cancer cells." (PMID 32714745, 2020).
epilepsy (3 papers, 2018 to 2025). A brain disorder characterized by episodes of abnormally increased neuronal discharge resulting in transient episodes of sensory or motor neurological dysfunction, or psychic dysfunction. "Moreover, PTPRM, PPFIA1, SLC1A2, and SGCE were confirmed to be associated with epilepsy, while PTPRD, ASB5, and MCU were involved in neurological disorders." (PMID 29568349, 2018).
cervical dystonia (2 papers, 2022 to 2023).
gastric cancer (2 papers, 2020 to 2022). A primary or metastatic malignant neoplasm involving the stomach. "Then, a novel TGF-β-associated prognostic model, including SRPX2, SGCE, DES, MMP7, and KRT17, was constructed, and the risk score was demonstrated as an independent prognostic factor for gastric cancer patients." (PMID 36467074, 2022).
alcohol abuse (1 paper, 2017). The use of alcoholic beverages to excess, either on individual occasions ("binge drinking") or as a regular practice. "Patients with myoclonus dystonia suffered more frequently from obsessive‐compulsive disorder and alcohol abuse, which might be partly caused by the mutation of epsilon‐sarcoglycan (SGCE) gene." (PMID 28239516, 2017).
Ataxia (1 paper, 2019). Ataxia refers to impaired coordination of voluntary muscle movement. "While ataxia is uncommon in DYT11 patients, it has been observed in individuals with SGCE mutations." (PMID 31868164, 2019).
cognitive decline (1 paper, 2019). "Cognitive problems including cognitive decline and psychomotor retardation have been reported in all but 5 genetic disorders, MYC/DYT‐SGCE, MYC/DYT‐KCTD17, mUDP7 (based on loss of SGCE‐gene), DYT‐ANO3, and the hyperekplexias." (PMID 31584223, 2019).
Cognitive impairment (1 paper, 2016). Abnormal cognition is characterized by deficits in thinking, reasoning, or remembering. "The deletion of SGCE gene has been related with psychosis and cognitive impairment, and might be responsible for the paranoid personality disorder of our patient." (PMID 27291887, 2016).
Glutaric Aciduria type 1 (1 paper, 2023). "The genetic dystonias were associated with the following genes: TOR1A, THAP1, SGCE, KMT2B, HPRT1 (Lesch Nyhan disease), PANK2 and GCDH (Glutaric Aciduria type 1)." (PMID 36445406, 2023).
hyperkinesia (1 paper, 2022). "Effective disease‐specific therapies included dopaminergic agents for neurotransmitters disorders, ketogenic diet for glucose transporter deficiency, and deep brain stimulation for SGCE‐, KMT2B‐, and GNAO1‐related hyperkinesia." (PMID 36054588, 2022).
microcephaly (1 paper, 2022). A congenital or acquired developmental disorder in which the circumference of the head is smaller than normal for the person's age and sex.
Parkinsonism (1 paper, 2024). Characteristic neurologic anomaly resulting from degeneration of dopamine-generating cells in the substantia nigra, a region of the midbrain, characterized clinically by shaking, rigidity, slowness of movement and difficulty with walking and gait. "Variants in none of the five implicated dystonia genes (TOR1A, SGCE, GNAL, THAP1 and KMT2B) have been reported to cause PD/parkinsonism to date." (PMID 39087914, 2024).
Tourette syndrome (1 paper, 2023). A neurologic disorder caused by defective metabolism of the neurotransmitters in the brain. "The patient's father, who was diagnosed in his childhood with Tourette's syndrome, also received genetic testing, which proved that to be a misdiagnosis and confirmed that he was the carrier of the SGCE mutation." (PMID 37846277, 2023).
Tremor (1 paper, 2024). An unintentional, oscillating to-and-fro muscle movement about a joint axis. "In particular, numerous monogenic neurodegenerative, neuropathic and metabolic diseases manifest with tremor often accompanied by signs of other movement disorders, especially of a dystonic (e.g. ANO3, SGCE), ataxic (e.g. PPPP2R2B, ATX3, TBP) or parkinsonian (e.g. LRRK2, FMR1, ATX3) type." (PMID 39346806, 2024).
Truncal dystonia (1 paper, 2017). Truncal dystonia is a form of focal dystonia (see this term), characterized by involuntary back arching often associated with pain and severe motor disability. "SGCE-mutation-negative patients may also display truncal dystonia, tics or tremor unusual for SGCE mutations." (PMID 28805718, 2017).
cancer (4 papers, 2020 to 2025). A tumor composed of atypical neoplastic, often pleomorphic cells that invade other tissues. "Although SGCE was reported to be a cancer risk gene in gastric cancer, colorectal cancer, hepatocellular carcinoma, and B-cell chronic lymphocytic leukemia, how it participates in cancer remains elusive." (PMID 37838174, 2023). "Such genes showed a lower proportion of monoallelic vs biallelic expression in cancer cell lines than some other imprinted genes, e.g., SNRPN, SGCE, NLRP2, H19, and ANO1." (PMID 40414875, 2025). "Conversely, RGS20, RPH3A, SGCE, and ZDHHC15 exhibited a substantial downregulation in their expression levels within the corresponding cancer cell lines." (PMID 38300336, 2024).
tumor (3 papers, 2011 to 2022). "However, since the function of SGCE and the mechanism of how it participate in tumor progression remains unknown up to now, its differential expression in HCC could only be regarded as a potential tumor-related marker without any concrete function." (PMID 21767414, 2011).
neurodevelopmental disorder (1 paper, 2022). A behavioral and cognitive disorder with onset during the developmental period that involves impaired or aberrant development of intellectual, motor, or social functions.
SGCE also shares sentences with these, for which no sentence is quoted: movement disorder (5 papers); Anxiety (3); Chorea (2); autosomal recessive limb-girdle muscular dystrophies (1); bipolar disorder (1); blepharospasm (1); cardiac arrhythmia (1); cardiomyopathy (1); cavernous cerebral malformations (1); COVID-19 (1); depression (1); dilated cardiomyopathy (1); endometriosis (1); Epileptic encephalopathy (1); episodic ataxia (1); Failure to thrive (1); generalized dystonia (1); genetic disorders (1); hyperekplexia (1); Lesch Nyhan disease (1); leukemia (1); limb girdle muscular dystrophies (1); metabolic disease (1); muscular dystrophy (1); Neurodevelopmental delay (1); neurological disorders (1); obsessive-compulsive disorder (1); paranoid personality disorder (1); psychiatric disorder (1); psychosis (1).
A further 3 diseases each share a sentence with SGCE in 1 paper.